SKA1 (spindle and kinetochore associated complex subunit 1)
Diseases named in the same sentence as SKA1 in open-access papers (continued):
Sharing a sentence is not in itself a finding about the gene and the disease.
cancer (continued). "Many previous studies have demonstrated the important role of SKA1 in the malignant transformation and progression of multiple cancer types, because this gene can regulate various signaling pathways to affect tumor cell growth and metastasis." (PMID 37814813, 2023). "We also demonstrated a correlation between SKA1/2/3 and the response to drug treatment across cancers and the promising potential of the SKA complex and its genes as therapeutic targets in cancer." (PMID 37180139, 2023). "We downloaded gene expression data and related clinical information data from the TCGA-LIHC database for patients with HCC and discovered that SKA1 was substantially differentially expressed in malignant tumors (P < .001)." (PMID 37746945, 2023). "The dysregulation of SKA1/2/3 expression is a common phenomenon in malignant tumors, indicating that the SKA family is significantly related to malignancy." (PMID 37180139, 2023). "Currently, the function and mechanisms of SKA1/2/3 in the development and progression of certain cancers are being increasingly studied." (PMID 37180139, 2023). "First, we used TCGA database to confirm that SKA1 was highly overexpressed in several malignant tumors, including HCC." (PMID 37746945, 2023). "It is evident that the signaling pathways mediated by SKA1 exhibit variations across different types of cancers." (PMID 37814813, 2023). "SKA1–3 affect the occurrence and development of several cancers and is a poor prognosis marker in lung cancer, esophageal carcinoma, and kidney renal papillary cell carcinoma (KIRP)." (PMID 36439516, 2022). "Several studies have demonstrated that SKA1–3 are involved in apoptosis and tumorigenesis, and their abnormal expression or activation is common in malignant tumors." (PMID 36439516, 2022). "In summary, SKA1–3 expression is correlated with cell apoptosis, proliferation, and cell cycle progression and connected to cancer patients’ poor prognosis." (PMID 36439516, 2022). "Recent studies reveal the involvement of SKA1 in the growth and proliferation of numerous cancer types." (PMID 36462498, 2022). "Functionally, SKA1 knockdown on ccRCC cells reduced cancer cell motility both in vivo and in vitro research." (PMID 36462498, 2022). "SKA1, a novel discovered gene, is the most studied gene in multiple cancer types among SKA family members." (PMID 34845974, 2021). "SKA1 was reportedly increased as a candidate oncogene in several common human cancers, contributing to various steps of oncogenesis and poorer prognosis." (PMID 32232899, 2020). "The role of SKA1 in the malignant progression of several cancers has already been discussed recently." (PMID 31827398, 2019). "Emerging evidence has demonstrated SKA1 as a candidate oncofetal protein that is involved in the development of a range of cancer types." (PMID 30537941, 2018). "Further studies are needed to elucidate the molecular mechanisms by which SKA1 are dysregulated in cancer, including HCC." (PMID 30537941, 2018). "Overexpression of SKA1 was detected in clinical specimens from patients treated with tyrosine kinase inhibitors and its expression contributed to cancer cell aggressiveness." (PMID 29928475, 2018). "Gene expression analysis showed that clonogenic side population cells in cancers express genes involved in the cell cycle and mitosis (e.g., SKA1, CCNB1, CDC25C, CDC2, BIRC5, CENPE, AURKB, KIFs, TOP2A, ASPM) more strongly than non-side population cells." (PMID 23962337, 2013). "Furthermore, these findings align closely with our own results, thereby suggesting that SKA1 represents a crucial candidate for personalized cancer therapy and a unique predictive marker for diagnosis and prognosis." (PMID 37814813, 2023). "To date, however, most studies on SKA1/2/3 in cancers are based on a single tumor or single gene." (PMID 37180139, 2023). "Therefore, SKA1–3 are useful prognostic biomarkers and potential therapeutic targets for several cancers." (PMID 36439516, 2022).
cancer (continued). "In HCC, SKA1–3 expression levels were all higher in cancer tissues than normal tissues." (PMID 36439516, 2022). "We came to the conclusion that since DUSP6 serves as a tumor suppressor in ccRCC, its overexpression may be to blame for the suppression of cancer cell migration and EMT brought on by SKA1 deficiency." (PMID 36462498, 2022). "The prognostic value and functional bioinformatics analysis of SKA1 also demonstrated that SKA1 might be a promising target for cancer gene therapy." (PMID 35095717, 2021). "Furthermore, we explored the protein expression profile of SKA1/2/3 in cell lines of various cancers in the CCLE database." (PMID 34845974, 2021). "Multiple studies have reported that SKA1 promotes cancer progression in a variety of tumors." (PMID 33224872, 2020). "We find that SKA1–3 are highly expressed in PDAC tissues relative to non-cancer tissues." (PMID 33224872, 2020). "Elevated levels of SKA1 have been shown to promote cancer cell proliferation and influence." (PMID 33224872, 2020). "Interestingly, several oncogenic signaling pathways, including ERK1/2, AKT, FAK and SRC, are regulated by expression of SKA1 in cancer cells." (PMID 29928475, 2018). "Recent data have revealed that SKA1 is involved in the development of cancer." (PMID 30537941, 2018). "Collectively, these data on the expression of SKA1 in HCC imply that SKA1 reactivation might be an important event during cancer development." (PMID 30537941, 2018). "In addition, studies have confirmed that the positively correlated co-expression genes NUSAP1, ASF1B, TPX2, and SKA1 are invariably involved in immune cell infiltration in numerous cancers, and thus contribute to the regulation of the tumor immune microenvironment." (PMID 38173030, 2024). "The reason why SKA1 expression is elevated in cancer remains unknown." (PMID 30537941, 2018). "All these findings indicated that cancer cells have similar gene expression profiling with fetal liver cells in HCC patients with high SKA1 level, and this type of gene profiling could promote cell proliferation by promoting cell cycle progression and reducing cell apoptosis." (PMID 30537941, 2018). "In addition, SKA1 has shown to be involved in the chemoresistance of cancer cells." (PMID 30537941, 2018). "We have also highlighted different signaling pathways, including molecules such as STAT3, SKA1, LPAR1 and Wnt β-catenin and their involvement in cancer development through the ZFAS1/miRNAs/mRNAs axis." (PMID 40109869, 2025). "Mechanistically, miR-10a-5p binds to the 3′ untranslated region of SKA1 mRNA, promoting its degradation and reducing SKA1 protein levels, thereby inhibiting the EMT process critical for cancer metastasis." (PMID 39796267, 2025). "Collectively, our data attest that SKA1 physically interacts with the SAFB and impels transcriptional repression of DUSP6, consequently provoking cancer aggressiveness." (PMID 36462498, 2022). "Taken together, these data corroborate that SKA1 physically interplays with SAFB, which induces SAFB-dependent transrepression of DUSP6, consequently promoting cancer aggressiveness." (PMID 36462498, 2022). "Furthermore, SKA1 appears to modulate the ERK1/2 and Akt signaling pathways in NSCLC cells, which play a crucial role in cancer progression." (PMID 37814813, 2023). "Moreover, MMP2 and MMP9, which were reported to be downstream of SKA1 or TRPV2 in many other cancers, were found to be downregulated in ESCC cells when SKA1 or TRPV2 was knocked down by siRNAs." (PMID 35813298, 2022). "According to our immunohistochemical results, SKA1 staining was positive in 97 (66.9%) PDAC cancer samples, while no or weak staining was observed in 48 cases (33.1%)." (PMID 32232899, 2020).
tumor (19 papers, 2013 to 2024). "A pathological study revealed that increased SKA1 expression levels in ccRCC tissues were associated with a more aggressive tumor phenotype." (PMID 36462498, 2022). "For example, upregulation of SKA1 expression in esophageal squamous cell carcinoma tissues is associated with tumor differentiation and pathological tumor node metastasis (TNM) stage." (PMID 34045512, 2021). "Immunohistochemistry revealed that increased SKA1 expression was present in 65 of the 126 cases and was significantly associated with higher serum alpha-fetoprotein concentration, larger tumor size and higher TNM stage." (PMID 30537941, 2018). "Previous studies have demonstrated that SKA1 upregulation is associated with higher tumor stage, aggressive phenotype and poor prognosis of patients." (PMID 30537941, 2018). "More recently, the gene encoding spindle and kinetochore associated protein 1 (SKA1) was identified as a target of anti-tumor miR-10a-5p." (PMID 29928475, 2018). "SKA1 was also upregulated in a subset of advanced oral premalignancies and promoted tumor-relevant properties in a corresponding cell line." (PMID 39656562, 2024). "SKA1 expression levels were significantly correlated with weight, age, T stage, N stage, M stage, tumor status, AFP levels, pathologic stages, histologic grade, OS, DSS, and PFI of the HCC patients." (PMID 37746945, 2023). "Several studies have suggested that SKA1/2/3 are involved not only in mitosis but also in apoptosis and tumor development." (PMID 37180139, 2023). "In the Cox regression model, univariate Cox regression indicates that the T stage (P < .001), M stage (P = .017), tumor status (P < .001), pathologic stage (P < .001), and SKA1 (P = .003) were correlated with a bad prognosis of HCC." (PMID 37746945, 2023). "Elevated SKA1 expression in HCC is associated with advanced clinicopathological features (AFP, histological grade, pathological stage, T stage, and tumor status), poor prognosis, and survival time." (PMID 37746945, 2023). "In fact, abnormal upregulation of SKA1 has been found in several tumor types, including stomach, lung, breast, ovarian, thyroid, and cervical cancers." (PMID 37814813, 2023). "Multivariate Cox regression analysis showed that tumor status (P = .006) and SKA1 (P = .007) were independent prognostic factors for OS." (PMID 37746945, 2023). "Logistic regression analysis revealed that SKA1 expression levels in HCC tissues were strongly linked to T stage, tumor status, histologic grade, age, and AFP levels." (PMID 37746945, 2023). "Consistently, lower SKA1 levels were detected in tumor sections derived from sh-SKA1-infected 786-O cells compared with their control counterparts." (PMID 36462498, 2022). "SKAs include SKA1–3 and play important roles in non-neoplastic diseases, such as obsessive-compulsive disorder; they also predict the development of post-traumatic stress disorder." (PMID 36439516, 2022). "Compared with the normal tissues, SKA1 expression was significantly higher in tumor tissues, except in the case of kidney chromophobes." (PMID 36439516, 2022). "It comprises three proteins (Ska1, Ska2, and Ska3) with theorized roles in chromosomal instability and tumor development, and its overexpression has been widely reported in a variety of tumors." (PMID 34045512, 2021). "In vitro experiments on the functional role of SKA1/2/3 support their potential carcinogenic value in BC tumor." (PMID 34845974, 2021).
tumor (continued). "Analysis of the tumor characteristics of the patients suggested that SKA1 and SKA3 overexpression was correlated with the IDH status and patient age." (PMID 35095717, 2021). "The member SKA1 was associated with alphafetoprotein (AFP), tumor size, and the TNM stage in patients with HCC and proliferation, the clinical stage and lymph node metastasis in NSCLC." (PMID 35095717, 2021). "According to the Oncomine database, we found that the transcriptional levels of SKA1/2/3 were highly expressed in various tumor types, including BC." (PMID 34845974, 2021). "As for biological behaviour, SKA1 acted as a tumour promotor in PDAC, overexpression of SKA1 facilitates cell proliferation, migration and invasion in vitro and in vivo." (PMID 32232899, 2020). "Increased SKA1 expression was significantly correlated with tumour size and cellular differentiation degree in PDAC tissues." (PMID 32232899, 2020). "We focused on spindle and kinetochore-associated complex subunits 1 and 3 (SKA1 and SKA3) because we recently reported that regulation of SKA1 by anti-tumor miR-10a-5p was involved in RCC pathogenesis." (PMID 29928475, 2018). "Gain of SKA1 expression was associated with higher serum AFP concentration, larger tumor size and higher TNM stage." (PMID 30537941, 2018). "At present, few research studies have examined the relationship between SKA1 expression and tumor development." (PMID 26063960, 2015). "At present, there are fewer researches on the relationship between SKA1 expression and tumor development." (PMID 26063960, 2015). "Among 123 tumor samples, 56 (45.5%) showed high SKA1 expression, with only 37% of the samples from normal adjacent tissues." (PMID 26063960, 2015). "SKA1 expression levels correspond to the degree of tumor infiltration by various immune cell types, and may play a role in the therapeutic response of patients with HCC." (PMID 37746945, 2023). "In this research, we discovered that SKA1 is essential for tumor metastasis." (PMID 36462498, 2022). "Similar to TCGA analysis, SKA1–3 expression levels were higher in tumor than normal tissues." (PMID 36439516, 2022). "In addition, little is understood about the potential processes and downstream targets of SKA1 in tumor metastasis." (PMID 36462498, 2022). "Correspondingly, RNA interference of SKA1 markedly decreased the mobility of tumor cells." (PMID 36462498, 2022). "Furthermore, we comprehensively explored the potential possibility of SKA1/2/3 exerting a tumor immunosuppressive effect in BC patients." (PMID 34845974, 2021). "In general, this study may contribute to providing a foundation for more understanding the molecular basis of SKA-mediated BC development, thereby providing valuable information on whether SKA1/2/3 could be used as potential tumor-promoting regulators of BC." (PMID 34845974, 2021). "Interestingly, the results of database analysis demonstrate the positive correlation between SKA1 expression and tumor stage in HER2-positive BC and its guiding value for prognosis." (PMID 34845974, 2021). "Considering that SKA1/2/3 may be implicated in the development and progression of BC, we further assessed the relationship between the SKA1/2/3 expression and the clinicopathological features (age and tumor stage) for patients with BC." (PMID 34845974, 2021). "Results reveal that the expression of SKA1 displayed a significant positive association with neutrophils infiltration and tumor purity, while a negative association with CD8 + T cells and macrophages infiltration (P < 0.05)." (PMID 34845974, 2021). "The knockdown of SKA1 inhibited invasion and migration and invasion of tumor cells." (PMID 35095717, 2021). "Finally, to evaluate the in vivo effect of SKA1, we performed subcutaneous xenograft assays in nude mice, and SKA1 overexpression significantly increased tumour growth, along with a marginally increased expression of Ki67." (PMID 32232899, 2020).
tumor (continued). "Interestingly, patients with high SKA1 expression tended to present greater tumour diameters compared with the low SKA1 expression group (P = .019)." (PMID 32232899, 2020). "Nevertheless, knockdown of SKA1 could sensitize tumor cells to tyrosine kinase inhibitor and epirubicin." (PMID 31827398, 2019). "SKA1 mRNA expression in ccRCC samples was evidently higher than in their corresponding normal counterparts, especially greater in metastatic tumor tissues than in normal and original tumor tissues, according to our initial analysis of the available clinical data sets TCGA (N = 72)." (PMID 36462498, 2022). "Moreover, the knockdown of SKA1 inhibited the migration and invasion of tumor cells." (PMID 34845974, 2021). "We then employed the Tumor Immune Estimate Resource (TIMER) database to undertake an immune infiltration study and investigate the link between SKA1 and tumor-related immunity." (PMID 37746945, 2023). "The expression of SKA1 and SKA3 in tumor free group were lower than the group with tumor, as well as the patient with vascular invasion." (PMID 36439516, 2022). "Interestingly, high expression of 4 genes targeted by anti-tumor miRNAs was significantly associated with poor prognosis of patients with RCC according to TCGA database analyses (UHRF1: p = 4.87E-06, LOXL2: p = 0.0343, PLOD2: p = 0.000855 and SKA1: p = 1.44E-07)." (PMID 29928475, 2018). "SKA1 and SKA3 expression levels were significantly increased in the more advance tumor stage and histological grade." (PMID 29928475, 2018). "Univariate Cox regression analysis showed that both death and relapse risk of HCC patients were increased with higher serum AFP, larger tumor size, late TNM stage and positive SKA1 expression." (PMID 30537941, 2018). "Additionally, in vitro and in vivo tests revealed that SKA1 successively speeds up the evolution of ccRCC and presumably aids cellular infiltration and dispersion by inducing EMT, an early stage in tumor metastasis." (PMID 36462498, 2022). "So, we speculated that high expression levels of SKA1 and SKA3, to some extent, may mediate tumor escape and inhibit the infiltration levels of immune cells." (PMID 33224872, 2020). "Furthermore, there existed strong co-expression of SKA genes not only in the normal dataset of GTEx but also in tumor datasets of TCGA and GSE62452, especially the correlation between SKA1 and SKA3 (r = 0.62, 0.6, and 0.69)." (PMID 33224872, 2020). "In xenograft models, we confirmed that knockdown of SKA1 could led to decreased N-cadherin and MMP9 and increased E-cadherin in xenograft tumor tissue." (PMID 31827398, 2019). "We observed differential expression of SKA1 in matched tissues, with more SKA1-expressing cells in the tumorous tissues than in the matched non-neoplastic tissues." (PMID 30537941, 2018). "The results indicated that SKA1 mRNA expression was significantly higher in tumorous tissues than that in non-neoplastic tissues (P < 0.001)." (PMID 30537941, 2018). "Moreover, relative to tumor-free survival patients, tumor-bearing patients significantly expressed high levels of SKA1 and SKA3 and both of them did not corelate with advanced pathological T (T3/4)." (PMID 33224872, 2020). "Both SKA1 and SKA3 were pivotal candidate genes targeted by miR-455-5p and miR-455-3p, respectively, and we hypothesized that the SKA complex was closely involved in RCC pathogenesis and could be regulated by several anti-tumor miRNAs in RCC cells." (PMID 29928475, 2018). "χ2 test showed that positive SKA1 expression was significantly correlated with higher serum AFP (P = 0.035), larger tumor size (P = 0.002) and late TNM stage (P = 0.009), but not with gender, age, differentiation or HBsAg." (PMID 30537941, 2018).
infection (1 paper, 2022). The state of being infected such as from the introduction of a foreign agent such as serum, vaccine, antigenic substance or organism. "DUSP6 expression plasmid co-infection, however, prevented the aggressive behavior brought on by SKA1 overexpression in ccRCC cells." (PMID 36462498, 2022).